S100A4 (S100 calcium binding protein A4)
Diseases named in the same sentence as S100A4 in open-access papers (continued):
Sharing a sentence is not in itself a finding about the gene and the disease.
heart failure (4 papers, 2014 to 2025). Inability of the heart to pump blood at an adequate rate to meet tissue metabolic requirements. "S100A4 expression in cardiomyocytes of patients suffering from hypertrophic cardiomyopathy was increased, and S100A4 was found to be upregulated following transition to heart failure." (PMID 35053115, 2022). "Interestingly, S100a4 mRNA has been up-regulated in the hypertrophic myocardium of the Dahl-rat hypertensive heart disease model and further activated during the transition to heart failure." (PMID 25101683, 2014). "In addition, C6 S100A4+ SMCs had higher scores for genes related to ferroptosis, oxidative stress and inflammation, which may indicate a new potential therapeutic approach for treating cardiomyopathy and preventing heart failure." (PMID 40717095, 2025).
inflammatory bowel disease (4 papers, 2013 to 2020). A spectrum of small and large bowel inflammatory diseases of unknown etiology. "S100A4 has been implicated in cancer and several inflammatory diseases, but its role in inflammatory bowel disease has not been well investigated." (PMID 28935867, 2017).
pancreatic adenocarcinoma (4 papers, 2013 to 2021). "In Logsdon’s datasets, S100A4 was found to be higher expressed in pancreatitis (fold change = 2.57), and pancreatic adenocarcinoma (fold change = 4.44) versus normal tissues." (PMID 34804125, 2021). "The role of S100A4 protein in in vivo tumor development was explored by knocking-down its expression in the human pancreatic adenocarcinoma MiaPACA-2 cell line using interfering RNA technology." (PMID 24023743, 2013). "Furthermore, it was found that S100A4 is overexpressed in pancreatic adenocarcinoma, most likely due to hypomethylation at intron 1 of the S100A4 gene." (PMID 32722137, 2020). "Immunohistochemical studies showed the co-expression of S100A4, FAK and Src protein in the same area of a lymph node metastasis from a human primary pancreatic adenocarcinoma sample." (PMID 25677816, 2015).
viral infection (4 papers, 2012 to 2025). "A few studies have also shown the various roles of S100A4 + cells in the pathogenesis of sexually transmitted viruses, which indicates that S100A4 is a promising target of viral infectious diseases." (PMID 34803967, 2021). "In order to investigate the expression patterns of s100a4 and s100a6 under general conditions that mimic bacterial and viral infection, the immunostimulation assay was carried out in PK-15 cells by using the LPS and Poly (I:C) as the stimulators." (PMID 22330747, 2012). "Similarly, in pathological conditions such as cancer, viral infection, and chronic inflammation, S100A4 is expressed in activated T cells, T-regs, and exhausted CD8 T cells." (PMID 40078995, 2025). "In line with this, studies using mouse models of chronic viral infection show that S100A4 expression is upregulated in exhausted CD8 T cells, suggesting that S100A4 expression may be a signature of exhausted CD8 T cells across different pathological conditions." (PMID 40078995, 2025).
ZIKV infection (4 papers, 2020 to 2025). "S100a4+ monocytes/macrophages also have been implicated in sustaining long-term Zika virus infection in the testes." (PMID 41031892, 2025). "Consistent with this, the CD45 + myeloid macrophage subpopulation located in mice testes, which is susceptible to ZIKV infection, comprised mainly of S100A4 + cells." (PMID 34803967, 2021). "Using ZIKV susceptible mice, we found that ZIKV infection attracted S100A4+ macrophages to accumulate in the testes and differentiate into interferon-γ-expressing cells." (PMID 33315931, 2020). "To address this question, we isolated S100A4+ macrophages from the peritoneal cavity and investigated their susceptibility to ZIKV infection." (PMID 33315931, 2020). "Deficiencies in S100A4 or interferon-γ signaling both reduced ZIKV infection in the seminiferous tubules." (PMID 33315931, 2020). "Here, we showed that S100A4+ macrophages, a myeloid macrophage subpopulation with susceptibility to ZIKV infection, facilitated ZIKV invasion and persistence in the seminiferous tubules." (PMID 33315931, 2020). "Additionally, S100a4 has been shown to increase the susceptibility of a macrophage subpopulation to Zika virus infection infection, thus facilitating virus invasion and persistence within the seminiferous tubules of testis." (PMID 41031892, 2025). "Susceptibility of S100A4+ macrophages to ZIKV infection was further investigated in vivo." (PMID 33315931, 2020). "S100A4+ macrophages originate from bone marrow and are susceptible to ZIKV infection." (PMID 33315931, 2020). "In contrast, niclosamide effectively reduces S100A4 + monocyte/macrophage infiltration, inhibits complement activation, alleviates testicular damage, and rescues the fertility of male mice from ZIKV infection." (PMID 37120617, 2023). "The authors find that spermatogenic cells are fragile to ZIKV infection and the complement system components produced by infiltrated S100A4 + monocytes/macrophages are crucial for the injury of spermatogenic cells." (PMID 37120617, 2023). "The results reveal the fragility of spermatogenic cells, especially spermatogonia, to ZIKV infection and show that the genes of the complement system are significantly upregulated mainly in infiltrated S100A4 + monocytes/macrophages." (PMID 37120617, 2023). "On the basis of niclosamide, we believe that the development of a derivative carrying both antiviral and anti-S100A4 potential will provide better protection for male health during ZIKV infection." (PMID 37120617, 2023). "At the late stage when spermatogenic cells are diminished, intraluminal S100A4+ macrophages replaced them to support ZIKV infection." (PMID 33315931, 2020). "To further investigate the roles of S100A4+ macrophages during ZIKV infection in testes, we generated S100a4-/-Ifnar-/- mice (SA6) by mating S100a4 deficient mice with A6 mice, and characterized with PCR." (PMID 33315931, 2020). "Identification of S100A4+ macrophages provides a novel therapeutic target for ZIKV infection, especially for its sexual transmission." (PMID 33315931, 2020). "The infection rate of each type of these cells was then determined by measuring the co-localization signals, and it was clear that S100A4+ macrophages replaced DDX4+ cells as the main target cells at late stage of ZIKV infection." (PMID 33315931, 2020). "How do S100A4+ macrophages overcome the immune suppressive properties of resident macrophages during ZIKV infection?" (PMID 33315931, 2020). "Our results suggested that S100A4+ macrophages played key roles in ZIKV infection in the testes and proposed a new model to understand ZIKV invasion and persistence in the seminiferous tubules." (PMID 33315931, 2020). "Here, we show that a bone marrow-derived S100A4+ macrophage subpopulation appeared in the testes of ZIKV-infected mice and were susceptible to ZIKV infection." (PMID 33315931, 2020).
ZIKV infection (continued). "To uncover the underlying mechanisms, we characterized the gene expression profile of ZIKV-infected mouse testes and selected S100A4+ macrophages as crucial factors for long-term ZIKV infection in testes." (PMID 33315931, 2020). "Taken together, these results showed that S100A4+ macrophages in the testes were derived from bone marrow and recruited to the testes during ZIKV infection." (PMID 33315931, 2020). "Taken together, these results demonstrated that niclosamide could save the fertility of male mice from ZIKV infection by inhibiting S100A4 expression and subsequent complement activation." (PMID 37120617, 2023). "Whether S100A4 directly functions in ZIKV infection through a sexually dimorphic mechanism remains to be determined." (PMID 34803967, 2021). "Increased S100A4+ cells after ZIKV infection were observed only in the spleen." (PMID 33315931, 2020). "Characterization of the origin and role of these macrophages might be helpful to further understand the contribution of S100A4+ macrophages to ZIKV infection in testes." (PMID 33315931, 2020). "S100A4+ macrophages were recruited to the interstitial space of ZIKV-infected testes at the early stage, differentiated into IFN-γ-expressing M1 macrophages and were highly susceptible to ZIKV infection." (PMID 33315931, 2020). "Among the top genes significantly increased upon ZIKV infection, S100a4 attracted our attention." (PMID 33315931, 2020). "Quantification further showed that DDX4+ spermatogenic cells significantly decreased after ZIKV infection whereas DDX4+ MAC+ spermatogenic cells, C1q+ cells, and S100A4+ cells were all increased, displaying features similar to those in A6 mice." (PMID 37120617, 2023). "In contrast, few F4/80 positive cells were observed in testes without ZIKV infection and they did not express S100A4, indicating testicular resident macrophages did not express S100A4." (PMID 33315931, 2020). "However, the ZIKV antigen was largely located in S100A4+ macrophages instead of DDX4+ spermatogenic cells at this time, indicating that intraluminal S100A4+ macrophages replaced spermatogenic cells to support ZIKV infection." (PMID 33315931, 2020). "Brain and lung tissues had few S100A4+ cells, and the number did not increase after ZIKV infection." (PMID 33315931, 2020). "No obvious difference in clinical manifestations and survival rate was found between SA6 and A6 mice, suggesting that S100a4 deficiency did not affect the susceptibility to ZIKV in general and that SA6 mice could serve as ZIKV infection model like A6 mice." (PMID 33315931, 2020).
allergic asthma (3 papers, 2021 to 2025). A asthma with a basis in a pathological type I hypersensitivity reaction. "S100A4 expression in CD8 T cells is increased in mouse models of allergic asthma and leads to CD8 effector memory T cell dysfunction." (PMID 40078995, 2025). "Recent reports have indicated that S100A4 activates proinflammatory pathways in airway smooth muscle tissues, and it is critical for mast cell activation in mouse models of allergic asthma." (PMID 37873538, 2023). "To further investigate the potential contribution of S100A4 to allergic asthma, we sensitized WT and S100A4-/- mice, a different strain of the S100A4 knockout mice in contrast to the strain we used before, with OVA/alum followed by OVA aerosol challenge." (PMID 34367151, 2021). "Our data demonstrated that airway inflammation, including inflammatory cell infiltration and cytokine production, typical features of allergic asthma, was suppressed in S100A4-/- mice." (PMID 34367151, 2021). "S100A4 can regulate the T cell-mediated immune response in allergic asthma." (PMID 40078995, 2025). "High level of S100A4 was found in the lung of mouse models with allergic asthma; additionally, the administration of S100A4-neutralizing antibodies in mice decreased inflammatory cell infiltration and accumulation in the lung and bronchoalveolar lavage fluid (BALF)." (PMID 37873538, 2023).
anaplastic thyroid carcinoma (3 papers, 2005 to 2020). "Targeting S100A4 siRNA has reported to decrease proliferation and induce apoptosis in anaplastic thyroid cancer (ATC) cells in vitro and in vivo, supporting that S100A4 is responsible for increased survival." (PMID 32842846, 2020). "We previously identified S100A4 as a candidate gene involved in anaplastic thyroid cancer metastasis by microarray analysis." (PMID 16265347, 2005). "We have previously demonstrated by microarray analysis that S100A4 was highly expressed in anaplastic thyroid carcinoma cell line with high metastatic potential (ARO/met2) as compared to its parental cell line ARO and found that S100A4 overexpression was associated with advanced disease stage." (PMID 16265347, 2005). "A proof of concept has already been demonstrated in a mouse model with anaplastic thyroid carcinoma, showing absence of metastasis in mice inoculated with S100A4-shRNA knockdown cells." (PMID 25880590, 2015).
astrocytic tumor (3 papers, 2008 to 2021). A glial tumor of the brain or spinal cord showing astrocytic differentiation. "Most of the reported intracellular effects of S100A4 are associated with cytoskeleton rearrangements that may influence cellular motility, and extracellulary added S100A4 has also been shown to boost migration of astrocytic tumor cells." (PMID 18554396, 2008). "High levels of S100A4 appeared typical of high-grade GBM, as low-grade astrocytic tumors displayed lower S100A4 content." (PMID 33918416, 2021). "In addition, the direct extracellular administration of S100A4 to astrocytic tumors modified their cytoskeletal arrangement and stimulated their migration rate, demonstrating a role also for the secreted protein in the migratory phenotype." (PMID 33918416, 2021).
atherosclerosis (3 papers, 2022 to 2023). A disease characterized by the build-up of fatty material and calcium deposition in the arterial wall resulting in partial or complete occlusion of the arterial lumen. "Sakic and his colleagues used a mouse model of atherosclerosis to demonstrate the neutralization of extracellular S100A4 and decreased areas of the atherosclerotic lesions." (PMID 36361563, 2022). "Downregulated genes (SYK, SMAD3, S100A4, and FERM3) were expected to be involved in inhibiting cellular recruitment by IPA, and were previously documented to enhance the beginning and progression of atherosclerosis." (PMID 35806463, 2022). "Thus, it will be important to decipher the complex relationship between apelin and S100A4, the mechanisms leading to apelin nuclear hijack and whether it might constitute a potential target in toning down SMC-driven atherosclerosis development." (PMID 37907514, 2023).
autoimmune pancreatitis (3 papers, 2009 to 2025). "Mice with S100A4/FSP1 Cre-mediated conditional knockout of TGFβR2 (Tgfbr2fspKO) spontaneously develop autoimmune pancreatitis by 6 weeks of age." (PMID 40078995, 2025).
breast adenocarcinoma (3 papers, 2010 to 2013). "Similar results were obtained with mouse monocyte/macrophage RAW 264.7, mammary adenocarcinoma CSML100 and human fibroblastic WI-38 cell lines (data not shown) indicating that suggested mechanism of S100A4 externalization is rather common." (PMID 20442771, 2010).
cardiomyopathy (3 papers, 2018 to 2025). A disease of the heart muscle or myocardium proper. "Based on these findings, it can be inferred that C6 S100A4+ SMCs are closely linked to the exacerbation of cardiomyopathy, potentially contributing to its progression." (PMID 40717095, 2025). "These insights open up exciting avenues for further exploration into the role of S100A4 in SMCs and its implications in cardiovascular health and disease, suggesting novel therapeutic targets and mechanisms underlying cardiomyopathies." (PMID 40717095, 2025). "The identification of PTN-NCL protein receptor pairs between C6 S100A4+ SMCs and ECs also provides a possible potential target for therapeutic intervention in cardiomyopathy." (PMID 40717095, 2025). "This led us to hypothesize a strong correlation between the C6 S100A4+ SMCs subpopulation and the pathogenesis as well as the adverse progression of cardiomyopathy." (PMID 40717095, 2025). "In summary, our comprehensive findings suggest that C6 S100A4+ SMCs may hold relevance to cardiomyopathies, particularly concerning cellular growth, stemness, and metabolic processes." (PMID 40717095, 2025). "Consequently, C6 S100A4+ SMCs may influence cardiomyopathies by promoting EC proliferation and migration through heightened KLF2 expression." (PMID 40717095, 2025). "Finally, as mentioned when selecting the C6 subtype, we conducted in vitro experiments to determine whether the knockdown of S100A4 similarly blocks cell growth and promotes apoptosis in SMCs, with the aim of exploring its role in cardiomyopathy, particularly in ICM." (PMID 40717095, 2025). "Some of these genes, including PTH1R, S100A4 and ADAM15, have been reported to be differentially expressed in DCM or other types of cardiomyopathies." (PMID 31948008, 2020).
cholangiocarcinoma (3 papers, 2012 to 2021). A carcinoma that arises from the intrahepatic biliary tree (intrahepatic cholangiocarcinoma) or from the junction, or adjacent to the junction, of the right and left hepatic ducts (hilar cholangiocarcinoma). "Paclitaxel has also been reported to inhibit invasion and hematogenous metastasis of cholangiocarcinoma by downregulating nuclear S100A4." (PMID 34078355, 2021). "In cholangiocarcinoma cell lines, S100A4-silencing leads to reduced motility, invasiveness, and MMP-9 secretion in vitro." (PMID 23166536, 2012). "Furthermore, it has been reported that nuclear expression of S100A4 protein is a biomarker for predicting increased invasiveness of cholangiocarcinoma and the phenomenon can be inhibited by using low-dose paclitaxel for targeting of S100A4 nuclear import." (PMID 29069865, 2017).
diabetic nephropathy (3 papers, 2017 to 2022). "In fact, a prior study demonstrated S100A4 expression in 86% of detached urine podocytes detected in patients with diabetic nephropathy." (PMID 29065913, 2017).
epilepsy (3 papers, 2018 to 2025). A brain disorder characterized by episodes of abnormally increased neuronal discharge resulting in transient episodes of sensory or motor neurological dysfunction, or psychic dysfunction. "The expression of the remaining four genes was upregulated in both datasets, with two of them (GFAP and S100A4) previously reported to be associated with epilepsy." (PMID 38212777, 2024). "As we have previously shown, S100A4 robustly protects neurons in animal models of brain trauma and epilepsy, and this effect is readily reproduced in corresponding in vitro models, in which neuronal death is induced by oxidative stress or KA excitotoxicity." (PMID 30083275, 2018). "Indeed, S100A4 mimetics that we have previously developed and demonstrated to be neuroprotective in animal models of brain trauma and epilepsy, also proved efficient in two in vitro models of PD." (PMID 30083275, 2018).
esophageal cancer (3 papers, 2013 to 2024). A primary or metastatic malignant neoplasm involving the esophagus. "Previous studies have associated S100A4 protein expression with survival in several tumor types, including bladder, colorectal, ovarian and esophageal carcinoma." (PMID 23760193, 2013). "MiR-21 has been shown to activate NFs and produce the CAF phenotypic markers SMA and S100A4, respectively in studies from colorectal and malignant esophageal cancer cells." (PMID 39187523, 2024). "A number of studies have suggested that S100A4 overexpression is correlated with poor clinical outcomes in various human cancers, such as bladder, colorectal, ovarian and esophageal carcinoma." (PMID 23760193, 2013). "In addition, propofol can also inhibit invasion and angiogenesis and induce apoptosis of esophageal cancer EC-1 cells in vitro by regulating the expression of S100A4." (PMID 34956562, 2021).
esophageal squamous cell carcinoma (3 papers, 2012 to 2015). Esophageal squamous cell carcinoma (ESCC) is a type of esophageal carcinoma (EC) that can affect any part of the esophagus, but is usually located in the upper or middle third. "Since it has been shown that S100A4 regulates the expression of invasion- and migration-associated genes, such as metalloproteases (MMPs), we next analyzed the mRNA levels of MMP2, which is known to be regulated by S100A4 in esophageal squamous cell carcinoma." (PMID 25738360, 2015).
hypertensive heart disease (3 papers, 2014 to 2025). Abnormal enlargement of the heart resulting from long-standing hypertension. "In the Dahl-rat hypertensive heart disease model, S100A4 is upregulated in hypertrophic myocardia and further activated during the transition to centripetal heart failure (HF)." (PMID 41195005, 2025).